ZNF124 (zinc finger protein 124)
Description:
May be involved in transcriptional regulation.
Synonyms: HZF16; HZF-16; ZK7
Tractability: PROTAC: ubiquitination databases record sites on it.
Gene: Protein-coding gene on chromosome 1 (247,121,975 to 247,172,046, reverse strand). Ensembl gene ENSG00000196418.
Subcellular location: Nucleus
Subcellular location (Human Protein Atlas): Nuclear membrane; Nucleoplasm
Pathways (Reactome):
Gene expression (Transcription): Generic Transcription Pathway
Gene Ontology:
Molecular function: protein binding; DNA binding; DNA-binding transcription factor activity, RNA polymerase II-specific; RNA polymerase II transcription regulatory region sequence-specific DNA binding
Biological process: regulation of transcription by RNA polymerase II; regulation of DNA-templated transcription
Cellular component: nucleus
Genetic constraint (gnomAD): Loss-of-function variants: 25 observed, 30.36 expected, observed/expected ratio (o/e) 0.82, 90% interval 0.6 to 1.15. The upper end of that interval is the gene's LOEUF score, 1.15, which puts it in group 5 of 6, group 1 being the genes least tolerant of losing a copy. Missense variants: 444 observed, 441.43 expected, observed/expected ratio (o/e) 1.01, 90% interval 0.93 to 1.09. Synonymous variants: 129 observed, 139.73 expected, observed/expected ratio (o/e) 0.92, 90% interval 0.8 to 1.07.
Homologues: Orthologues: chimpanzee ZNF124 (100% identical), macaque ZNF124 (80% identical), mouse Zfp78 (43% identical), Drosophila melanogaster CG3281 (31% identical), Drosophila melanogaster Phs (28% identical), Drosophila melanogaster CG2712 (28% identical). Paralogues in human: ZNF69 (58% identical), ZNF20 (57% identical), ZNF439 (55% identical), ZNF440 (55% identical), ZNF555 (50% identical), ZNF77 (49% identical), ZNF778 (48% identical), ZNF560 (47% identical), ZNF669 (47% identical), ZFP37 (46% identical), ZNF805 (46% identical), ZNF558 (46% identical), and 50 more.
Diseases named in the same sentence as ZNF124 in open-access papers:
ZNF124 is named in the same sentence as 12 diseases in open-access papers, as found by Europe PMC text mining. Sharing a sentence is not in itself a finding about the gene and the disease. The quoted sentences say what the papers report.
lung carcinoma (2 papers, 2019 to 2023). "As indicated, circ_ZNF124 expression was much higher in these lung cancer cell lines than normal epithelial cell BEAS-2B (**P < 0.01)." (PMID 31754348, 2019). "The expression of circ_ZNF124, miR-337-3p and JAK2 (Janus Kinase 2) in lung cancer cell lines and normal epithelial cells were detected by qRT-PCR (quantitative real-time PCR)." (PMID 31754348, 2019).
bladder cancer (1 paper, 2025). "In cisplatin-resistant bladder cancer cell lines, FLRT2, HOXC5, SCD, GRM7, HMGA1, ETV7, and SCO2 were highly expressed, while EMP1, SERPINA6, and ZNF124 exhibited lower expression levels." (PMID 39744172, 2025).
breast carcinoma (1 paper, 2025). "LPA's connection to Imiquimod, as well as to Megestrol Acetate—a drug commonly used against breast cancer—may be analogous to the relationships observed with ZNF124 and HMGA1." (PMID 39744172, 2025).
leukemia (1 paper, 2013). A malignant (clonal) hematologic disorder, involving hematopoietic stem cells and characterized by the presence of primitive or atypical myeloid or lymphoid cells in the bone marrow and the blood. "ZNF124 (ZK7) mRNA expression was detected in several human tissues such as a number of leukemia cell lines." (PMID 23874428, 2013).
lung adenocarcinoma (1 paper, 2019). A carcinoma that arises from the lung and is characterized by the presence of malignant glandular epithelial cells. "In particular, hsa_circ_0017348 derived from ZNF124 was found highly overexpressed in lung adenocarcinoma tumor tissues." (PMID 31754348, 2019). "Among them, cir_ZNF124 was found to be highly expressed in lung adenocarcinoma." (PMID 31754348, 2019). "Previous genome-wide transcriptome profiling found circ_ZNF124 was highly expressed in lung adenocarcinoma, however, the role of circ_ZNF124 in non-small cell lung cancer (NSCLC) is still unknown." (PMID 31754348, 2019).
myeloma (1 paper, 2025). "A sequencing study on myeloma revealed that the Zinc Finger Protein 124 (ZNF124) is predominantly expressed in the most aggressive tumor subgroups, correlating with an adverse prognosis." (PMID 39744172, 2025).
retinal degeneration (1 paper, 2026). Degeneration of the retina. "To elucidate the pathogenesis of the mutation, we generated a retina-specific knockout mouse model of ZNF124 murine homologous gene Gm20541, which manifested RP-like phenotypes characterized by reduced electroretinogram response and progressive retinal degeneration." (PMID 41708596, 2026).
Retinal dystrophy (1 paper, 2026). Retinal dystrophy is an abnormality of the retina associated with a hereditary process. "Integrated analysis of RNA-seq data from both Gm20541 and Msx2 mutant retinas indicated that ZNF124 is essential for maintaining normal retinal function by regulating Msx2 transcription, which in turn controls the expression of murine homologues of retinal dystrophy genes Rs1, Pde6g, and Pdc." (PMID 41708596, 2026).
tumor (5 papers, 2019 to 2025). "Interestingly, we show that ZNF124 knockdown inhibits tumor cell growth and increases cell death specifically in G3-MB cells but not in SHH-MB cells, suggesting a unique role of ZNF124 in regulating the growth of the most aggressive G3 MB cells." (PMID 33681213, 2021). "According to the expression levels and regression coefficients, the downregulated BAX, PWP2, SERTAD1, S1PR4, ZFAND1, NUDT13 and ZNF107 with HR < 1 were considered as tumor suppressors, whereas the MVD, BAD, CPNE7, CPNE7, UTP23 and ZNF124 upregulated with HR > 1 were regarded as oncogenes." (PMID 36685828, 2022).
cancer (2 papers, 2021 to 2025). A tumor composed of atypical neoplastic, often pleomorphic cells that invade other tissues. "Moreover, circ-ZNF124 is implicated in the progression of non-small cell lung cancer, one of the most aggressive types of cancer with the majority of diagnosis at advanced stages." (PMID 34205978, 2021). "circ-ZNF124 negates the miR-337-3p-mediated repression of JAK2/STAT3, and the consequent activation of this pathway increases cancer cell growth, migration, and colony formation abilities." (PMID 34205978, 2021). "Across all cancer cell lines, we observed that many more genes were depleted rather than enriched in these screens, with DPH5, ZNF124, ABL1, and HNF4A showing the most significant toxicity." (PMID 39870664, 2025).
ZNF124 also shares sentences with these, for which no sentence is quoted: bladder tumor (1 paper); non-small cell lung carcinoma (1).